HGF (hepatocyte growth factor)
Diseases named in the same sentence as HGF in open-access papers (continued):
Sharing a sentence is not in itself a finding about the gene and the disease.
breast carcinoma (continued). "In contrast, we observed high basal Brk activity in serum-starved T47D breast cancer cells cultured in the absence of HGF." (PMID 20687930, 2010). "Notably, inhibitors of the HGF/c-Met and TGF-β signaling pathways, such as Cabozantinib27 and Fresolimumab28, have been involved in clinical trials for breast cancer and showed benefits in metastasis patients, suggesting their potential as novel therapies for breast cancer." (PMID 40665092, 2025). "In addition to MMP-2 and MMP-9, MMP-1 has also been used as an accurate marker in a three markers scores model, including MMP-1, hepatocyte growth factor, and chemokine ligand 5, to predict axillary lymph node metastasis (LNM) positivity in breast cancer patients." (PMID 37181043, 2023). "Cultivating three different types of breast cancer cell lines by CM derived from young and senescent HPMCs, it was observed that the secretory levels of pro-angiogenic agents, including CXCL1, CXCL8, the hepatocyte growth factor (HGF), and the VEGF, were significantly increased in cancer cells." (PMID 37046588, 2023). "Similarly, serum levels of hepatocyte growth factor (HGF) were elevated, which is secreted by stromal cells, including ASCs, during obesity, and its receptor, tyrosine-protein kinase Met (c-Met), is expressed on breast cancer cells." (PMID 36010901, 2022). "HGF/MET aberrant activation plays important roles in the development and progression of several human cancers including lung, renal, gastrointestinal, thyroid, and breast carcinomas, as well as sarcomas and malignancies of the nervous system such as GBM among others." (PMID 35626056, 2022). "These authors expressed a chimeric receptor containing the β4 cytoplasmic domain in MDA-MB-435 breast cancer cells and showed that the β4 chimera was tyrosine phosphorylated upon stimulation with hepatocyte growth factor (HGF), but did not enhance HGF-induced Akt and ERK1/2 phosphorylation." (PMID 33883672, 2021). "However, many studies have revealed that very high concentrations of HGF (i.e., greater than 10 ng/mL) can induce EMT and increases the tumor invasiveness of certain types of cancer cells, such as gastric cancer cells, breast cancer cells, and LNCaP prostate cancer cells." (PMID 31590238, 2019). "Similarly, the HGF produced by adipose-derived stem cells (ASCs), together with the c-MET expressed in primary breast carcinoma cells, increases tumor cell migration, metastasis and self-renewal through PI3K-mediated GS3K inactivation and β-catenin stabilization and nuclear accumulation." (PMID 30352967, 2018). "Increased serum HGF (sHGF) has been reported to be a negative prognostic marker in various malignancies including colorectal cancer, gastric cancer, prostate cancer, ovarian cancer, breast cancer, glioma, melanoma, and multiple myeloma." (PMID 29069748, 2017). "Interestingly we found that breast cancer cells expressed increased levels of beta-catenin and phosphorylated GSK3 after co-culture with ASCs, suggesting HGF/cMet crosstalk could induce beta-catenin activation by GSK3 inhibition (cc)." (PMID 24327602, 2014). "Moreover, recombinant HAI-1 could suppress the conversion of pro-HGF/HGF to the mature form in HGF/SF-expressing MRC-5 fibroblasts, while also inhibiting fibroblast-mediated breast cancer cell invasion." (PMID 25268161, 2014). "We here aimed to observe the effect of SOCS7 knockdown on the behaviour of breast cancer both in vitro and in vivo and to investigate whether SOCS7 knockdown in breast cancer cells MCF7 (ER +ve) and MDA-MB-231 (ER −ve) can affect their in vitro growth and migrational responses when treated with HGF." (PMID 25162020, 2014). "Therefore, we speculated that PKCζ may be involved in HGF-induced CXCR4 expression in breast cancer, and may affect the behaviors of migration and invasion in breast cancer cells." (PMID 22242160, 2012).
breast carcinoma (continued). "Moreover, intratumoral injection of HGF conspicuously increased the number of mice with lung and liver metastasis but not the size of breast cancer xenografts." (PMID 22242160, 2012). "Consequently, the IL-7/HGF/LIF/VEGF cluster has been identified as a functional module that orchestrates multiple processes, including development, angiogenesis, stem cell maintenance, and the establishment of an immunosuppressive phenotype within the breast cancer microenvironment." (PMID 41597220, 2026). "In addition, activation of the HGF‐MET pathway has been reported as a clinically relevant resistance mechanism in a variety of tumors, including trastuzumab resistance in HER2‐positive breast cancer, BRAF inhibitor resistance in melanoma, and bevacizumab resistance in glioblastoma." (PMID 36416133, 2023). "Hence, our finding that MACC1 overexpression is closely related to the clinical outcome of breast cancer warrants further and in-depth investigation on whether and how MACC1 interacts with the HGF-c-MET pathway, or other signaling pathways, in this highly prevalent malignancy." (PMID 23497677, 2013). "Thus endogenous host (mouse cells) derived HGF may not stimulate the growth of human breast cancer cells transplanted in athymic mice." (PMID 23762292, 2013). "The cytotoxic effects were more pronounced in the cancer cell lines, particularly the MDA-MB-231 breast cancer and RT4 bladder cancer cells, compared to the non-cancerous hGF and ARPE-19 cells." (PMID 40005959, 2025). "In breast cancer (MCF-7, MDA-MB-231 and BT-474) inhibits proliferation, migration and G1/S cell cycle progression through suppression of Hepatocyte Growth Factor (HGF)-induced c-Met activation, without affecting non-tumorous cells (MCF10)." (PMID 41465505, 2025). "Our results suggested that treatment with HGF and/or BFE did not appear to have any bearing on the activity or expression levels of these factors within these breast cancer cell lines." (PMID 30314527, 2018). "OC also significantly inhibited the proliferation of several human breast cancer MDA-MB-231, MDA-MB-468 cell, MCF-7 cells, BT-474 cells and T-47D cells, with or without induction by hepatocyte growth factor (HGF) or 17β-oestradiol." (PMID 29734791, 2018). "RAPGEF2 degradation-failure leads to inhibition of hepatocyte growth factor (HGF)-induced cell migration and expression of non-degradable RAPGEF2 suppressed metastasis of human breast cancer cells." (PMID 24904820, 2014). "In contrast, in the low invasive/nonmetastatic breast cancer cell line T47D, which had no detectable MET and CDCP1 expression, ectopic MET expression stimulated the HGF-dependent activation of invasive activity, and concomitant CDCP1 expression activated SRC and further promoted invasive activity." (PMID 35085554, 2022). "In conclusion, we have identified that TGFβ1 regulates HGF‐induced and MET‐mediated cell migration, through positive regulation of C‐ets‐1 and negative regulation of miR‐128‐3p expression in basal‐like breast cancer cell lines and in triple‐negative breast cancer tissue." (PMID 30004628, 2018). "Analysis of The Cancer Genome Atlas database showed that, unlike primary PIK3CA‐wild‐type and HER‐2+ breast carcinomas, PIK3CA‐mutant tumors display increased expression of AXIN2, HGF, STAT3, IGF‐1, and IGF‐2 mRNA and activation of AKT, IGF1‐MTOR, and WNT canonical signaling pathways." (PMID 28296140, 2017).
melanoma (201 papers, 2006 to 2026). A malignant, usually aggressive tumor composed of atypical, neoplastic melanocytes. "Resistance to MEK inhibitors has been associated with HGF in melanoma while resistance to PI3K inhibitors has been associated with AREG, among other factors." (PMID 40411295, 2025). "Like with other kinase receptors, abnormal activities of Met and HGF have been associated with cancers such as melanoma." (PMID 38732242, 2024). "In this study, we show that PTEN expression correlates with progression to the metastatic state in human melanomas, and provide an experimental link using an HGF-transgenic, PTEN-deficient mouse melanoma model." (PMID 36824269, 2023). "It has been shown that HGF secreted by fibroblasts causes the primary insensitivity of melanoma cells to PLX4720 (BRAF inhibitor) as a result of the simultaneous activation of the MAPK and PI3K/AKT pathways." (PMID 35565444, 2022). "A translational study found that high blood neutrophil counts in melanoma patients refractory to immunotherapy were associated with high serum HGF levels." (PMID 36010840, 2022). "The release of HGF leading to HGFR activation was associated with resistance to BRAF inhibition in melanoma." (PMID 33918490, 2021). "Our thesis is corroborated by the fact that we have recently shown that administration of EGF and HGF on melanoma cells causes a decrease in the filamentous to monomeric actin ratio, what was correlated with cells’ increased invasive potential." (PMID 29719603, 2018). "Increased GD3 expression promoted melanoma cell adhesion to surrounding tissues and susceptibility to HGF present in the tumor microenvironment, leading to synergy of multiple extracellular signals in melanoma tissue." (PMID 29773994, 2018). "PHA-665752, another c-MET inhibitor, inhibited the migration of NRAS-mutated melanoma cells toward HGF." (PMID 30513872, 2018). "During malignant progression, UV-induced HGF/SF melanomas also frequently exhibit loss or inactivating mutations within regions of the p16INK4ACDKN2A gene that encode the p16INK4A tumor suppressor protein." (PMID 28788083, 2017). "A previous study indicated that HGF facilitates resistance to BRAF inhibitor in malignant melanoma cells with an oncogenic BRAF mutation." (PMID 27683122, 2016). "Transgenic mice overexpressing hepatocyte growth factor/scatter factor (HGF/SF) have extra-follicular dermal melanocytes, notably in the papillary upper dermis, and are susceptible to UV-induced melanoma." (PMID 24223113, 2013). "Pigmented HGF/SF neonatal mice are more susceptible than albino HGF/SF animals to UVA -induced melanoma, indicating an involvement of melanin in melanoma formation." (PMID 24223113, 2013). "The lack of distinguishing histopathological characteristics associated with primary melanomas of the HGF+ × [m1m2]+/− strain was surprising in light of the strong pro-metastatic effect of NM23 deficiency." (PMID 22699362, 2013). "Such mutations are rarely if ever seen in the HGF mouse melanoma model, which is probably a consequence of constitutive RAF activation downstream of the cell surface receptor for HGF, the MET tyrosine kinase." (PMID 22699362, 2013). "Dysfunctional receptor tyrosine kinase (RTK) signaling, in particular through the hepatocyte growth factor (HGF) tyrosine kinase receptor c-Met signaling pathway, is one important hallmark of melanoma." (PMID 19274086, 2009). "Our data suggest that the enhanced activation of p70S6K by HGF might compensate for the loss of cell division in abemaciclib-treated cells and thus contribute to abemaciclib resistance in metastatic UM melanoma cells." (PMID 33806615, 2021). "It remains unclear as to whether this effect is caused by the upregulation of HGF in fibroblasts following BRAFi therapy or whether the use of these inhibitors results in the recruitment of HGF-expressing fibroblasts into the melanoma niche." (PMID 33430277, 2021).
melanoma (continued). "The HGF/SF model may not be appropriate for testing of inhibitors of mutant BRAF, the constitutive MET activity and consequent downstream activation of BRAF in HGF/SF melanomas likely precludes the genesis of BRAF-activating mutations." (PMID 28788083, 2017). "In addition to the direct role of MET signalling in melanoma, HGF expression by stromal cells has been linked to innate resistance to RAF inhibitor treatment in melanoma patients." (PMID 28103611, 2017). "In light of the DNA repair and transcription functions of NME1, we are also using NextGen sequencing to compare mutational and transcriptional profiles in UV-induced melanomas (both primary and metastatic tumors) between the HGF/SF and HGF/SF × NME1/2+/− hybrid strains." (PMID 28788083, 2017). "Notably, gene expression analysis of the ARF-deficient and INK4a-deficient melanomas arising in our HGF/SF transgenic mice also identified MCL-1 as one of the top overexpressed genes associated with more malignant melanomas." (PMID 27846237, 2016). "The addition of hepatocyte growth factor (HGF) to BRAF-mutated melanoma cell lines confer resistance to BRAFi, hence stromal cells producing large amounts of HGF may be responsible for intrinsic resistance to therapy with BRAFi." (PMID 25344914, 2014). "HGF/SF melanomas also exhibit a number of other characteristics that resemble the human form of the disease, such as the junctional activity observed between melanoma and epithelial cells in skin, and loss of the tumor suppressor CDKN2A during malignant progression." (PMID 28788083, 2017). "Notably, larger melanomas (>5 mm) in the hybrid strain were associated with a significantly higher incidence of lymph node involvement and lung metastasis than seen with similarly-sized melanomas of the HGF/SF strain." (PMID 28788083, 2017). "In BRAF-mutant melanomas, CAF-derived HGF has been implicated in resistance to BRAF inhibitors by reactivating the MAPK signaling pathway, thereby allowing melanoma cells to evade therapeutic pressure." (PMID 40649909, 2025). "In another study, quercetin dose-dependently suppressed hepatocyte growth factor (HGF)-mediated melanoma cell migration and invasion by the inhibition of c-Met phosphorylation, reduced c-Met homo-dimerization and decreased c-Met protein expression." (PMID 39337397, 2024). "Met (mesenchymal–epithelial transition factor receptor), along with its paracrine-induced ligand HGF (hepatocyte growth factor), is another signaling pathway that has been targeted for melanoma therapy." (PMID 38732242, 2024). "Recently, the correlation of NOX4 with another pathway involved in the different stages of melanoma, the hepatocyte growth factor (HGF)/c-met axis, has been analyzed." (PMID 39334716, 2024). "What is unique about Met in melanoma cell lines is that HGF is secreted via autocrine and paracrine signaling, often leading to a positive feedback loop of growth." (PMID 38732242, 2024). "The hepatocyte growth factor/MET pathway also plays a key role in melanoma development, progression, and therapeutic resistance." (PMID 39596009, 2024). "Given the role of c-MET in melanoma invasion and migration, and its association with adhesion molecules and EMT processes, the involvement of c-MET/HGF signalling in anoikis resistance is unsurprising." (PMID 37181747, 2023). "HGF/MET signaling has been recognized to have an etiopathogenetic role in melanoma progression and metastasis, as well as immune microenvironment modulation and therapeutic resistance." (PMID 37496665, 2023). "A group of researchers stated that quercetin showed anti-metastatic activity in melanoma by inhibiting c-Met phosphorylation, reducing its homodimerization, and ultimately suppressing the HGF/c-Met signaling pathway." (PMID 36926328, 2023). "HGF is crucial for melanoma proliferation, survival, motility, invasiveness, distant metastatic niche formation, and the acquisition of resistance to oncoprotein-targeted drugs." (PMID 37762344, 2023).
melanoma (continued). "Hepatocyte growth factor (HGF)-mediated activation of C-Met signaling has been proposed as a therapeutic aim for melanoma metastasis." (PMID 36926328, 2023). "A study by Koefinger and others demonstrated that expression of HGF in melanoma cells induces a switch in cadherin expression from E-to N-cadherin, driven by the downregulation of Slug and upregulation of Twist." (PMID 37181747, 2023). "For several malignancies such as non-small-cell lung cancer (NSCLC), breast, ovarian, and gastric cancers and melanoma, acquired resistance frequently involves activation of the HGF/Met pathway." (PMID 36672409, 2023). "Melanoma and non-small cell lung cancer (NSCLC) had the highest frequency of HGF genetic alteration (> 8%) with mutation as the main variation." (PMID 37828456, 2023). "C-Met, the HGF receptor, is over-expressed in BCC, SCC, and melanoma indicating the compelling dependence of skin tumors on HGF mitogenic activity." (PMID 37762344, 2023). "Studies subsequently established that melanoma cells with high c-MET/HGF autocrine signalling have an increased propensity for metastasis to the liver." (PMID 37181747, 2023). "In melanoma, aberrant HGF/Met signaling can promote melanoma metastasis by enhancing Ezrin expression via the Sp1 transcription factor." (PMID 37371090, 2023). "In particular, in BRAF-mutated melanomas, CAF-produced HGF was able to activate the MAPK and AKT pathways in tumor cells, thus compensating for BRAF switch-off and sustaining resistance." (PMID 36324182, 2022). "Immunohistochemical (IHC) analysis of BRAF V600E melanoma patient-derived biopsies highlighted that patients with abundant stromal HGF showed a poorer response to BRAF inhibitors than those lacking stromal HGF." (PMID 36324182, 2022). "Our in vivo investigations of selenium included a prevention study using the hepatocyte growth factor (HGF) mouse model of UV-induced melanoma." (PMID 36291795, 2022). "Activated fibroblasts also affect melanoma drug resistance development among others through the production of hepatocyte growth factor (HGF), basic fibroblasts growth factor (bFGF), and neuregulin 1, which support cell proliferation and tumor growth." (PMID 35538545, 2022). "In transgenic mice overexpressing HGF, ultraviolet-B exposure promoted the early appearance of rapidly enlarging primary melanomas, showing enhanced invasive and metastatic behaviour." (PMID 36007304, 2022). "HGF is secreted not only by fibroblasts but also by melanoma cells stressed with such factors as drugs, and reduced glucose or oxygen concentration (hypoxia)." (PMID 35565444, 2022). "This study demonstrates that the ablation of either Nme1 or Nme2 confers robust increases in metastatic activity in the HGF-based mouse model of UV-induced melanoma." (PMID 33024267, 2021). "Several studies showed that HGF promotes melanoma progression by favouring the switch from E- to N-cadherin and downregulating desmoglein 1 expression." (PMID 34067929, 2021). "Normal melanocytes express c-Met and are receptive to HGF; however, melanoma cells produce HGF, creating an autocrine loop that constantly activates the c-MET receptor." (PMID 33807778, 2021). "Stimulation of the HGF/MET pathway strengthens numerous processes that are essential for melanoma development and construction of visceral metastatic niche." (PMID 34885093, 2021). "It has been reported that patients suffering from melanoma with detected HGF secretion by tumor stroma exhibited a much weaker response to BRAFi treatment compared to patients negative for stroma-derived HGF." (PMID 33430277, 2021). "In a spontaneous mouse model of melanoma, MDSCs recruited to the tumor site produced HGF and TGF-β to induce EMT, while depletion of MDSCs suppressed melanoma metastasis." (PMID 34576042, 2021). "Immunohistochemistry analysis of paraffin sections from melanoma patients shows a positive correlation between stromal HGF, innate resistance to treatment and poor response to MAPKi therapy." (PMID 34067929, 2021).